IGFBP5 (insulin like growth factor binding protein 5)
Diseases named in the same sentence as IGFBP5 in open-access papers (continued):
Sharing a sentence is not in itself a finding about the gene and the disease.
metabolic disorders (2 papers, 2013 to 2024). "Consequences of higher IGFBP-5 expression levels for metabolic complications have not been analyzed in detail yet; however, these findings suggest a possible involvement of IGFBP-5 in the development of metabolic disorders in abdominal adipose tissue." (PMID 24340035, 2013).
neurodegenerative disease (2 papers, 2022 to 2024). A disorder of the central nervous system characterized by gradual and progressive loss of neural tissue and neurologic function. "Future studies should clarify whether the observed upregulation of IGFBP5 is specific for AD or whether an increase in IGFBP5 expression is generally expected in neurodegenerative diseases or brain injury." (PMID 35513854, 2022).
neurological diseases (1 paper, 2023). "Local inhibition of IGFBP5 expression may provide a new treatment strategy for diabetic ED and other ischemic vascular or neurological diseases." (PMID 35866351, 2023).
IGFBP5 also shares sentences with these, for which no sentence is quoted: systemic sclerosis (6 papers); neuroblastoma (5); astrocytomas (3); ependymoma (3); head and neck squamous cell carcinoma (3); leukemia (3); Anxiety (2); Cachexia (2); metastatic melanoma (2); polycystic ovarian syndrome (2); retinoblastoma (2); acute myeloid leukemia (1); adenocarcinoma (1); adenoma (1); age (1); anxiety disorder (1); autoimmune disease (1); bipolar disorder (1); cholangiocarcinoma (1); chronic inflammatory demyelinating polyradiculoneuropathy (1); chronic rhinosinusitis (1); connective tissue disorder (1); Crohn disease (1); diffuse large B-cell lymphoma (1); dilated cardiomyopathy (1); dysplasia (1); endocrine disorders (1); endometrial carcinoma (1); endometrial stromal sarcoma (1); esophageal squamous cell carcinoma (1).
A further 53 diseases each share a sentence with IGFBP5 in 1 paper.